UBAP1 (ubiquitin associated protein 1)
Description:
Component of the ESCRT-I complex, a regulator of vesicular trafficking process. Binds to ubiquitinated cargo proteins and is required for the sorting of endocytic ubiquitinated cargos into multivesicular bodies (MVBs). Plays a role in the proteasomal degradation of ubiquitinated cell-surface proteins, such as EGFR and BST2.
Synonyms: UBAP-1; NAG20; SPG80; UAP; UBAP
Tractability: Antibody: its Gene Ontology location is reachable by antibodies, with high confidence. PROTAC: ubiquitination databases record sites on it; its protein half-life has been measured.
Gene: Protein-coding gene on chromosome 9 (34,179,005 to 34,252,523, forward strand). Ensembl gene ENSG00000165006.
Subcellular location: Cytoplasm, cytosol; Endosome
Subcellular location (Human Protein Atlas): Cytosol; Plasma membrane; Vesicles
Pathways (Reactome):
Disease: Budding and maturation of HIV virion; HCMV Late Events; Membrane binding and targetting of GAG proteins
Autophagy: Late endosomal microautophagy
Vesicle-mediated transport: Endosomal Sorting Complex Required For Transport (ESCRT)
Gene Ontology:
Molecular function: protein binding; ubiquitin binding
Biological process: ubiquitin-dependent protein catabolic process via the multivesicular body sorting pathway; membrane fission; multivesicular body assembly; protein transport to vacuole involved in ubiquitin-dependent protein catabolic process via the multivesicular body sorting pathway
Cellular component: cytoplasm; cytosol; endosome; ESCRT I complex; endosome membrane
Genetic constraint (gnomAD): Loss-of-function variants: 5 observed, 36.95 expected, observed/expected ratio (o/e) 0.14, 90% interval 0.07 to 0.28. The upper end of that interval is the gene's LOEUF score, 0.28, which puts it in group 1 of 6, group 1 being the genes least tolerant of losing a copy. Missense variants: 482 observed, 616.94 expected, observed/expected ratio (o/e) 0.78, 90% interval 0.72 to 0.84. Synonymous variants: 208 observed, 231.45 expected, observed/expected ratio (o/e) 0.9, 90% interval 0.8 to 1.01.
Homologues: Orthologues: chimpanzee UBAP1 (97% identical), macaque UBAP1 (97% identical), dog UBAP1 (95% identical), guinea pig UBAP1 (92% identical), rat Ubap1 (91% identical), mouse Ubap1 (91% identical), pig UBAP1 (91% identical), rabbit UBAP1 (90% identical), tropical clawed frog ubap1 (59% identical), zebrafish ubap1 (39% identical), Drosophila melanogaster CG10435 (20% identical). Paralogues in human: UBAP1L (21% identical).
Diseases named in the same sentence as UBAP1 in open-access papers:
UBAP1 is named in the same sentence as 21 diseases in open-access papers, as found by Europe PMC text mining. Sharing a sentence is not in itself a finding about the gene and the disease. The quoted sentences say what the papers report.
hereditary spastic paraplegia (8 papers, 2020 to 2024). Hereditary spastic paraplegias (HSP) comprise a genetically and clinically heterogeneous group of neurodegenerative disorders characterized by progressive spasticity and hyperreflexia of the lower limbs. "Mutations in the UBAP1 gene have been identified as a cause of the neurodegenerative disorder Juvenile-onset hereditary spastic paraplegias (HSPs)." (PMID 39649166, 2024). "Finally, we show that expression of a UBAP1 mutant identified in patients with hereditary spastic paraplegia and associated with disrupted ESCRT function, increases steady-state STING-dependent type I IFN responses in healthy primary monocyte-derived dendritic cells and fibroblasts." (PMID 36739287, 2023). "Based on our time-resolved map, we also show that expression of a UBAP1 mutant found in patients with hereditary spastic paraplegia leads to post-Golgi accumulation of activated STING with consequent constitutive induction of type I IFN." (PMID 36739287, 2023). "A lack of UBAP1 leads to neurological disorders via the ESCRT pathway, such as hereditary spastic paraplegia." (PMID 35268118, 2022).
Spastic paraplegia (3 papers, 2020 to 2025). Complete loss of the ability to move the lower limbs accompanied by spasticity of the lower limbs. "c.371dupT, encoding the truncated UBAP1 protein with 72.6% missing of the normal amino acid sequence, is responsible for the spastic paraplegia (SPG) in this family." (PMID 35321509, 2022). "Through further inspection of newly available 100KGP data and other neurological probands that were excluded from the case-control analysis dataset, we identified two additional patients with spastic paraplegia and UBAP1 truncating variants." (PMID 32934340, 2020). "The limitation of our study was the lack of genetic testing for the proband's family in confirming the diagnosis of UBAP1 gene spastic paraplegia due to financial constraints." (PMID 39801705, 2025).
breast carcinoma (2 papers, 2017 to 2021). "UBAP1 has also been reported fused, in-frame, with UBAP2 in one breast cancer tumor, with ADAMTSL1 in one low grade glioma." (PMID 28423358, 2017).
Juvenile onset (2 papers, 2022 to 2025). Onset of signs or symptoms of disease between the age of 5 and 15 years. "SPG80, caused by UBAP1 (ubiquitin-associated protein 1) mutations, is a pure form of juvenile-onset HSP reported recently." (PMID 35962060, 2022).
diabetes mellitus (1 paper, 2024). A metabolic disorder characterized by abnormally high blood sugar levels due to diminished production of insulin or insulin resistance/desensitization. "The high expression groups of PENK, EFEMP2, UBAP1, MAFF and KLF4 were mainly concentrated on diabetes mellitus (DM)." (PMID 38332532, 2024).
Dyskinesia (1 paper, 2022). A movement disorder which consists of effects including diminished voluntary movements and the presence of involuntary movements. "Ubap1+/E176Efx23 knock-in mice developed progressive hindlimb dyskinesia from an early stage." (PMID 35962060, 2022).
gout (1 paper, 2020). A condition characterized by painful swelling of the joints, which is caused by deposition of urate crystals. "Two variants (rs1189081296 and rs962251804) were simultaneously associated with UBAP1 methylation and gout." (PMID 32630231, 2020). "Causal inference testes showed that UBAP1 methylation mediated relationships between variants (rs1189081296 and rs962251804) and gout." (PMID 32630231, 2020). "In this study, several variants located in UBAP1 and RAPTOR were associated with gout, and causal inference tests revealed that the effects of genotypes on gout appeared to be mediated by CpG methylation changes." (PMID 32630231, 2020). "Therefore, hypermethylation of UBAP1 potentially reduces UBAP1 transcription and intensifies IL-1β production, exacerbating gout." (PMID 32630231, 2020). "In conclusion, this study provided evidence of aberrant methylation changes of PGGT1B, INSIG1, ANGPTL2, JNK1, UBAP1, RAPTOR, and CNTN5 in gout." (PMID 32630231, 2020). "In gout patients, seven aberrant DNA methylation sites that were mapped to seven genes (PGGT1B, INSIG1, ANGPTL2, JNK1, UBAP1, RAPTOR, and CNTN5) and survived genetic and meQTL analyses or causal inference tests were discovered." (PMID 32630231, 2020). "Given the roles of PGGT1B, INSIG1, ANGPTL2, JNK1, UBAP1, RAPTOR, and CNTN5 in regulating IL-1β or gouty inflammation and differential methylation of these genes in gout, the next important topic is the consequence of manipulating the respective signaling pathways." (PMID 32630231, 2020). "Six (PGGT1B, INSIG1, ANGPTL2, JNK1, UBAP1, and RAPTOR) were novel genes in the field of gout." (PMID 32630231, 2020). "Moreover, measuring transcription factors identified in this study and chromatin immunoprecipitation (ChIP) for these transcription factors would provide more clues about the mechanistic link between PGGT1B, INSIG1, ANGPTL2, JNK1, UBAP1, RAPTOR, and CNTN5 methylation and gout." (PMID 32630231, 2020). "Taken together, these results suggested that relationships between PGGT1B, INSIG1, ANGPTL2, JNK1, UBAP1, RAPTOR, and CNTN5 methylation and gout were not confounded by genetic mediators." (PMID 32630231, 2020).
Parkinsonism (1 paper, 2020). Characteristic neurologic anomaly resulting from degeneration of dopamine-generating cells in the substantia nigra, a region of the midbrain, characterized clinically by shaking, rigidity, slowness of movement and difficulty with walking and gait. "Additional clinical features included parkinsonism and learning difficulties, but their association with UBAP1 needs to be established." (PMID 32934340, 2020). "The size of this analysis does not allow to correlate the presence of parkinsonism with the identified pathogenic variants in UBAP1." (PMID 32934340, 2020).
Pseudomonas infection (1 paper, 2017). Infections with bacteria of the genus pseudomonas. "PumA ensures efficient inhibition of innate immune responses by interacting with MyD88 and TIRAP, key adaptor proteins for IL‐1R and the main relevant TLRs in Pseudomonas infection (TLR4 and TLR5), as well as UBAP1 which regulates cytokine receptor pathways." (PMID 28483816, 2017).
cancer (4 papers, 2017 to 2025). A tumor composed of atypical neoplastic, often pleomorphic cells that invade other tissues. "In conclusion, dual CRISPR screens identified ATG9A and UBAP1 as crucial regulators of cancer cell susceptibility to CAR-macrophage-induced cytotoxicity." (PMID 40595560, 2025). "We observed a significant reduction in ATG9A KO and UBAP1 KO cancer cells compared to control cancer cells when cocultured with macrophages." (PMID 40595560, 2025). "Our screen identified ATG9A along with several ESCRT genes (UBAP1, CHMP6, and VPS25) as critical determinants of the cancer cell response to macrophages." (PMID 40595560, 2025). "Neither UBAP1 nor TGM7 has a function that, based on known functionally relevant cancer-specific fusions (typically kinases, transcription factors, chromatin modifiers), is readily connected to tumorigenesis, therefore, it is difficult to speculate what role this fusion might serve." (PMID 28423358, 2017).
tumor (4 papers, 2009 to 2021). "For example, for mammalian ESCRT-I, there are single genes for the VPS23 [also called TSG101 (tumour susceptibility gene 101)] and VPS28 subunits, but four variants of VPS37 (VPS37A–D) and three variants of MVB12 (MVB12A/B and UBAP1)." (PMID 30190330, 2018). "SPLUNC1, UBAP1, BRD7, NAG7, NOR1, NGX6 and LTF genes were found to be tumor suppressor/susceptibility genes in different stages of NPC." (PMID 19949542, 2009). "UBAP1 is originally derived from the tumor-suppressor locus in human chromosome 9p21–22." (PMID 34191852, 2021). "Like HD-PTP, UBAP1 is important for EGFR degradation and α5β1 integrin turnover, and is a candidate tumour suppressor." (PMID 30190330, 2018). "Cellular gene alterations also contribute to NPC development, especially inactivation of tumor suppressor genes, such as SPLUNC1, UBAP1, BRD7, NOR1, NGX6 and LTF, which are involved in different stages of NPC initiation and progression." (PMID 19949542, 2009).
infection (1 paper, 2017). The state of being infected such as from the introduction of a foreign agent such as serum, vaccine, antigenic substance or organism. "This is consistent with PumA targeting of UBAP1 and enhancing its activity during infection in vitro." (PMID 28483816, 2017). "Consistent with our hypothesis, wild‐type PA7 decreases the levels of TNFR1 in A549 cells in a PumA‐dependent manner suggesting targeting of UBAP1 is occurring during infection and could enhance its activity." (PMID 28483816, 2017). "To establish a link between PumA interaction with UBAP1 and the ability of PumA to reduce TNFα‐dependent signalling (Fig EV5A), we analysed the levels of TNFR1 during infection." (PMID 28483816, 2017).
UBAP1 also shares sentences with these, for which no sentence is quoted: nasopharyngeal carcinoma (2 papers); autosomal dominant pure HSP (1); bronchiectasis (1); Charcot-Marie-Tooth disease (1); glioma (1); hyperuricemia (1); neurodegenerative disease (1); neurological disorders (1); prostate carcinoma (1).